TLR4 (toll like receptor 4)
Diseases named in the same sentence as TLR4 in open-access papers (continued):
Sharing a sentence is not in itself a finding about the gene and the disease.
cancer (continued). "In contrast, HMGB1 release from dying cancer cells can activate anticancer immunity: the complex of HMGB1 with RAGE or Toll-like receptor 4 (TLR4) triggers cascades of reaction that lead to the local secretion of proinflammatory cytokines, including IL−1, IL−6 and TNF-α." (PMID 32698492, 2020). "Interestingly, TLR-4 expression results in bordering proliferative trends in cancer stem cells (CSC) and GBM." (PMID 32354122, 2020). "At the same time, activated-TLR4 expressed on immune cells is essential to anti-cancer immunity." (PMID 33469538, 2020). "TLR4 agonists induce maturation of dendritic cells (DCs), promoting the immune response of cancer-antigen specific cytotoxic T cells, which ultimately kill cancer cells." (PMID 33469538, 2020). "Previous studies mentioned that TLR-4 plays a crucial role in various diseases, especially cancer." (PMID 32414062, 2020). "Combined with the KEGG enrichment data, it can be determined that TLR4 might promote intestinal tumorigenesis by activating cytokine‐cytokine receptor interaction and pathways in cancer signalling pathways." (PMID 31650683, 2020). "After combining these results with KEGG enrichment data, it was determined that TLR4 might promote intestinal tumorigenesis by activating cytokine‐cytokine receptor interaction and pathways in cancer signalling pathways." (PMID 31650683, 2020). "TLR4 signaling in cancer cells and leukocytes mediate inflammation related to oncogenesis." (PMID 33306717, 2020). "TLR4 has a strong relation with inflammatory response and cancer progression." (PMID 32823757, 2020). "Since TLR polymorphisms have been associated with changes in susceptibility to many diseases, including cancers and TLRs promote the survival of cancer cells, we also correlated the coexistence of previously genotyped TLR (TLR2, TLR4 and TLR9) polymorphisms with the VDR polymorphisms." (PMID 32471257, 2020). "TLR4 could modulate immunosuppressive cytokine induction and apoptosis resistance, events responsible of cancer cells’ immune escape." (PMID 32492880, 2020). "This suggests that TLR4 could even be widely used as a primary target for suppressing inflammation-related cancers." (PMID 33469538, 2020). "Earlier data showed that RID inhibited signaling through two inflammation-related receptors, TNFR and TLR-4, in several human cancer cell lines; these observations were validated by measuring inhibition of NF-κβ signaling, JNK signaling, and chemokine secretion." (PMID 32655311, 2020). "Furthermore, increased expression of TLR4 correlates with upregulation inflammatory cytokines and higher possibility of cancer recurrence in CRC patients." (PMID 32210720, 2020). "TLR4 agonists have been proposed as immunotherapeutics in cancer." (PMID 32132528, 2020). "In addition, sB7-H3 induced VEGF and IL-8 secretion via the TLR4/NF-κB pathway, supporting the idea that sB7-H3 promotes invasion and cancer cell metastasis." (PMID 33306717, 2020). "We investigated whether the anti-cancer effect of PPARγ is through regulating TLR4 signaling pathway." (PMID 32665906, 2020). "In their study, TLR4 expression in carcinoma tissues mirrored that in the normal mucosa." (PMID 32424768, 2020). "Toll‐like receptor 4 (TLR4) plays an essential role in cancer progress." (PMID 30957973, 2019). "Lipopolysaccharide (LPS) can interact with Toll-like receptor 4 (TLR4), leading to the activation of nuclear transcription factor-kappa B (NF-κB), a transcription factor that plays an important role in both inflammation and cancer." (PMID 30871017, 2019). "Furthermore, increased TLR4 expression and responsiveness has been shown in PCa cells compared to non-cancer prostate cells." (PMID 32010622, 2019). "Hence, it is assumed that HMGB1-mediated TLR4 signaling is involved in NET-induced cancer cell migration." (PMID 31034495, 2019).
cancer (continued). "Recent studies also supported the immunological mechanism of action of P-MAPA through the activation of TLR2 and TLR4 signaling in both cancer and infections, in addition to regulating the activity of T cells (especially CD4+T and CD8+T cells) and natural killer (NK) cells." (PMID 31861351, 2019). "Recently identified interaction between CB2 and TLR4 and their co-expression, co-precipitation and co-functioning in macrophage activation and cancer progression might be one possible example for these protein complexes." (PMID 31616248, 2019). "On the cancer part, the release of Hsp70/90-containing EVs extracts free amino acids from the body’s largest pool of proteins, skeletal muscle, perhaps to satisfy its need for rapid growth, by activating TLR4 systemically." (PMID 31480237, 2019). "Systemic activation of TLR4 by cancer can alter the homeostasis of other organs." (PMID 31480237, 2019). "The possible role of TcpC in cancer could be related with its known activity as an antagonist of Toll-like receptor 4, an activity that promotes aberrant tissue inflammation." (PMID 30717148, 2019). "Additionally, CRBN inhibited TRAF6-induced ubiquitination of BECN1 (Beclin 1), and that induced autophagy activation in CRBNKD THP-1, CRBN-knockout (CRBNKO) H1299, and CRBNKO MCF7 cancer cells in response to TLR4 stimulation." (PMID 31620128, 2019). "The mechanistic study may further explore correlation of pro- and anti-apoptotic markers with hallmarks of cancer inflammatory markers such as TLR-4, p38, p65, pERK and pJNK." (PMID 31521140, 2019). "In this study, we identified 40S ribosomal protein S3 (RPS3) through a pull-down assay using a variety of human cancer cell-derived proteins that could bind to TLR4." (PMID 30819254, 2019). "Also, crucial DAMPs such as extracellular HMGB1 contribute to enhanced ICD by binding to toll-like receptor 4 (TLR4) on dendritic cells, potentiating cancer immunotherapy." (PMID 31695807, 2019). "Observations of chronic bleeding in various cancers leads us to hypothesize that Hb and Hb degradation products released from lysed RBC near cancer nests might modulate local TLR4-positive cells." (PMID 31163699, 2019). "However, the role of the TLR4-NFκB signaling pathway during differentiation of cancer stem-like cells has been poorly studied." (PMID 29679017, 2018). "In particular, Toll-Like Receptor 4 (TLR4) has been described to be involved in the inflammatory processes observed in several pathologies (such as ischemia/reperfusion injury, neuropathic pain, neurodegenerative diseases, and cancer)." (PMID 29686833, 2018). "In contrast, IL-6, IL-8 and XIAP levels were reduced in TLR4-knockdown cancer cells." (PMID 29486738, 2018). "Meanwhile, some researchers have revealed roles for TLR4-activated signaling pathways in cancer." (PMID 29338742, 2018). "In addition to these signaling pathways, the classical TLR4/MyD88 signaling pathway is also responsible for cancer progression." (PMID 29338742, 2018). "In contrast, cancer cells expressed TLR4 diffusely throughout the cytoplasm even in the nucleus." (PMID 29670922, 2018). "PAUF and TLR4 expression gradually increased from benign to cancer." (PMID 30111860, 2018). "And TLR4 plays a key role in connecting inflammation and cancer invasion and progression." (PMID 29308184, 2018). "And TLR4 induced ROS production to significantly increase cancer cell proliferation as well." (PMID 30250402, 2018). "EGCG can upregulate Tollip (Toll-interacting protein) and down-regulate of TLR4 expressions via 67LR may be effective in the anti-cancer activity." (PMID 30213077, 2018). "Moreover, due to the wide activation of NF-κB in cancers, the efficiency of Galectin-3/TLR4/NF-κB/NEAT1 path should be compared with NF-κB activation induced by other factors in vitro and in vivo." (PMID 29788922, 2018). "Recently, it has been reported that a TLR4 agonist may play an important role as an immunomodulator in the treatment of cancer." (PMID 29977867, 2018).
cancer (continued). "Moreover, the use of Mtb heparin-binding hemagglutinin and the TLR4 agonist, HspX, in adjuvant treatment of cancer was recently reported." (PMID 29637049, 2018). "The inappropriate cut-off value may influence the capability of TLR4 to predict prognosis in patients with cancer." (PMID 29560134, 2018). "Therefore, a meta-analysis was conducted to assess the prognostic value of upregulated TLR4 in cancer patients." (PMID 29560134, 2018). "Undoubtedly, NF-kB plays a pivotal role in the TLR4-mediated signaling in cancer cells." (PMID 29343281, 2018). "The engagement of TLR4 signaling in cancer was revealed by previous studies." (PMID 30111860, 2018). "PAUF and TLR4 were more frequently expressed in carcinoma than benign or borderline tumor." (PMID 30111860, 2018). "In addition, cancer-induced activation of TLR4 on immune cells would increase their synthesis and release of inflammatory cytokines that promote muscle catabolism." (PMID 28536426, 2017). "Indeed, HA has been shown to promote the proliferation and migration of cancer cells by interacting with TLR4 and knockdown of TLR4 inhibited these effects of HA." (PMID 28460475, 2017). "Furthermore, depletion of toll-like receptor 4 (TLR4) or neutralization of IL-10 in M2 macrophages blocked the EMT ability of cancer cells." (PMID 29379802, 2017). "This is in accordance with the recent cellular and animal studies which indicated that PD-L1 expression in cancer cells could be upregulated by TLRs, especially TLR4 stimulation aside from the inducibility of INF-γ." (PMID 28484456, 2017). "Our data suggest that TLR4 is a central mediator of cancer-induced muscle protein degradation through the UPP and the ALP, and thus may be a key therapeutic target of cancer cachexia." (PMID 28536426, 2017). "Our data suggest that TLR4 is a specific mediator of cancer-induced muscle catabolism." (PMID 28536426, 2017). "TLR4 is expressed in various cancers and functions in cancer biology." (PMID 28881826, 2017). "Therefore, TLR4 activation is likely to exert extensive pathological impact on various organs and thus a key contributor to the etiology of cancer cachexia." (PMID 28536426, 2017). "The relationship between TLR4 signaling and tumorigenesis is complex and involves both innate and adaptive immunity, with evidence showing that TLR4 signaling can enhance or suppress cancer development, depending on the model system." (PMID 28531216, 2017). "The correlation between cancer tissue expressed TLR4 and PD-L1 were then observed." (PMID 28484456, 2017). "Besides, TLR4 expression level in cancer samples was inversely correlated with serum sTLR4 level in patients with early-stage NSCLC (r = −0.485, P = 0.003)." (PMID 28484456, 2017). "Additionally, the interaction between HMGB1 and TLR4 mediates anti-cancer immunity during radio- and/or chemotherapy." (PMID 29246127, 2017). "Recent studies showed that stimulation of TLR4 could induce PD-L1 dynamic expression on DCs, macrophages, colonic stromal cells, and cancer cells." (PMID 28484456, 2017). "TLR2 and TLR4 agonists, Coley toxin (mixture of killed Streptococcus pyogenes and Serratia marcescens bacteria) and Bacillus Calmette-Guerin have become long-used therapeutic drugs against cancers." (PMID 28216575, 2017). "The significance of cancer expressed TLR4 in cancer-related inflammation has also been outlined." (PMID 28484456, 2017). "Consequently, the inverse correlation of cancer expressed TLR4, and patients’ outcome has been reported." (PMID 28484456, 2017). "TLR4 activation is central to the progression of hepatic fibro-inflammatory disease and carcinoma." (PMID 28423574, 2017). "The role of TLR4 signaling in cancer has been considered a double-edged sword." (PMID 26883191, 2016). "Toll-like receptor 4 (TLR4) is important in promoting the immune response in various cancers." (PMID 26675260, 2016).
cancer (continued). "In this context, it would be interesting to assess whether M3G increases invasiveness of cancer cell lines that express TLR4." (PMID 27909407, 2016). "However, herein, we used TLR4 agonist LPS as a tool to address how and when to use adjuvants to improve cancer immunotherapy." (PMID 26885368, 2016). "Previous studies have shown TLR4 expression in various cancer types." (PMID 27008696, 2016). "Cytoplasmic TLR4 expression increased towards dysplasia and cancer." (PMID 27008696, 2016). "We therefore evaluated three polymorphisms in NFKB1 and TLR4 and their possible interaction with diet and life style factors in a prospective cohort of 1010 CRC cases and 1829 randomly selected participants from the Danish Diet, Cancer and Health Study." (PMID 25705893, 2015). "BLS signaling via TLR4 could contribute to the success of cancer treatment in combination therapies." (PMID 25973756, 2015). "This signaling is required for optimal proliferation and protection against apoptosis in the injured intestine, while TLR4 may lower the threshold for carcinogenesis in an AOM-induced cancer model." (PMID 26504896, 2015). "In addition to calreticulin exposure, late apoptotic or necrotic release of HMGB-1 from dying cells, and subsequent binding to TLR-4 on dendritic cells was necessary to obtain optimal antigen presentation of chemotherapy or radiotherapy treated cancer cells." (PMID 25688334, 2015). "TLR4 participates in innate immunity in various ways, not only in resistance to Gram-negative bacterial infections, but also in many autoimmune and inflammatory disease settings, including atherosclerosis, diabetes mellitus, cancer, and rheumatoid arthritis." (PMID 26576220, 2015). "The present study focused on TLR4 and its prognostic value in cancer therapy." (PMID 25360699, 2014). "Four cancers displayed high expression, and 14 cancers showed low expression of TLR4." (PMID 25547486, 2014). "The TLR4 and NF-kB pathways may collaborate in inflammation and cancer, and eHsp90 facilitates the secretion of inflammatory cytokines via a TLR4-NF-kB pathway in vascular cell types." (PMID 24805867, 2014). "Moreover, the blockade of TLR4 by siRNA and NF-κB inhibitors decreases the invasive ability of cancer cells." (PMID 25120541, 2014). "At the same time, additional studies suggest the protective role of TLR4 in cancer." (PMID 25120541, 2014). "Indeed, reports about the regulation of TLR4 or other TLRs signaling pathways in cancer cells have been few." (PMID 25179302, 2014). "The associated levels of TLR4 & MyD88 mRNA were statistically unaltered between the MyD88 positive and negative cancers (p = 0.8777 and 0.1348, respectively)." (PMID 24977712, 2014). "Currently, most of the TLR4 antagonists are being evaluated against cancer-unrelated symptoms." (PMID 25076949, 2014). "An anti-HMGB1 antibody or specific inhibitor (i.e. glycyrrhizin) or targeting its proposed receptors (RAGE and the toll-like receptor 4, TLR4) on cancer cells may prevent or inhibit the development of drug resistance." (PMID 25512109, 2014). "TLR4 expression on various cancer cells suggests that TLR4 signaling may play a crucial role in cancer development and immunity." (PMID 25179302, 2014). "TLR2 and TLR4 are major TLRs and have been actively investigated in inflammation and cancer." (PMID 24376595, 2013). "A dataset composed of 14627 cases and 17438 controls from 34 publications were included in a meta-analysis to evaluate the association between overall cancer risk or cancer-specific risk and three SNPs of TLRs (TLR2 −196 to −174 del, TLR4 rs4986790 and rs4986791)." (PMID 24376595, 2013). "In cancer cells, higher expression of TLR4 was localized in the cytoplasm and in the cell membrane." (PMID 24030146, 2013). "However, the intensity of staining for TLR4 in malignant tumors was considerably greater than that in normal tissues or benign tumors." (PMID 22533866, 2012).
cancer (continued). "In addition, 40 (48 %) cancers showed a high-level combined expression of TLR4/MyD88 (6+: 17, 7+: 15, 8+: 8)." (PMID 22533866, 2012). "We will focus on reports concerning TLR4 signaling and its involvement in cancer development and progression as well as the therapeutic benefit that could come from TLR4 stimulation." (PMID 22110526, 2011). "TLR4 signaling in cancer is considered a double-edged sword." (PMID 22110526, 2011). "Further research of the role and mechanisms of TLR4 activation in cancer may provide novel antitumor vaccine adjuvants as well as TLR4 inhibitors that could prevent inflammation-induced carcinogenesis." (PMID 22110526, 2011). "Additionally, TLR4 elicits appropriate immune activation in various types of cancer such as lung, ovary, stomach and colorectum." (PMID 22180778, 2011). "Since TLR, and in particular TLR4, are in focus of molecular cancer therapy development, such results might open the door to set up prospectively planned RCTs that include TLR4 genotype information while evaluating new and advanced treatments of HNSCC." (PMID 21854645, 2011). "It is possible that with upregulation of MTDH induced by LPS, the secretion of cytokines such as MMPs increased greatly and could degrade the extracellular matrix which then further activated the TLR4 and enhanced the invasive ability of cancer cells." (PMID 22195048, 2011). "MPLA is the only TLR4 agonist that has been clinically tested as an adjuvant for cancer vaccines." (PMID 22110526, 2011). "The use of systemically delivered TLR4-siRNA may provide a novel approach to preventing cancer progression and survival." (PMID 20618976, 2010). "In addition, 25 (23%) cancers showed a high-level combined expression of TLR4/MyD88 (5+: 12, 6+: 5, 7+: 7, and 8+: 1)." (PMID 20145615, 2010). "In tumors, cancer cells exhibited high expressions, especially of TLR4 and TLR9." (PMID 21129170, 2010). "Our findings suggest that TLR4/MyD88 signalling contributes to CRC tumourigenesis not just in colitis-associated cancer but also in sporadic CRC." (PMID 20145615, 2010). "Moreover, various studies have shown a relationship between TLR4 activation (the receptor for LPS) and cancer progression." (PMID 18937865, 2008). "Because HMGB1-deficient cancers may have limited capacity to recruit inflammatory cells through secretion of HMGB1, it was speculated that TLR4 agonists may be able to substitute HMGB1 in its role of activating T cells by binding to TLR4." (PMID 40804938, 2025). "Additionally, it is essential to explore whether TLR-4 inhibitors could be utilized in cancer therapy to enhance the efficacy of commonly used drugs." (PMID 40404908, 2025). "As a member of the toll-like receptor family, TLR-4 is involved in the first-line defense of the innate immune system formed by the body's mucous membranes, playing a role in pathogen recognition and inducing an innate immune response in the fight against inflammation and cancer." (PMID 40404908, 2025). "Therefore, the question of whether to target TLR-4 agonists or antagonists for the treatment of cancer remains unresolved in science." (PMID 39770406, 2024). "Present data suggests that both TLR4 and MyD88 have been involved in the progression of multiple cancers, but they also demonstrate a protective role when stimulated or inhibited depending on the cancer type or stage; thus, two TLR4 ligands have already been approved for cancer treatment." (PMID 39000291, 2024).